IL18 (interleukin 18)
Diseases named in the same sentence as IL18 in open-access papers (continued):
Sharing a sentence is not in itself a finding about the gene and the disease.
multiple system atrophy (1 paper, 2024). Multiple system atrophy (MSA) is a neurodegenerative disorder characterized by autonomic failure (cardiovascular and/or urinary), parkinsonism, cerebellar impairment and corticospinal signs with a median survival of 6-9 years. "Other works revealed increased levels of interferon γ, IL-10, IL-18, IL-1β, IL-4, IL-6, transforming growth factor β1, and Tumor Necrosis Factor-α in PSP and Multiple System Atrophy when compared to PD." (PMID 39176092, 2024).
muscle atrophy (1 paper, 2022). The loss of muscle tissue due to inactivity or disease. "Our in vivo work also shows that targeting HMGB1/IL-18 signaling rescues muscle-specific differentiation marker expression in glycerol-induced muscle injury, which indicates that targeting IL-18 is worthwhile for the treatment of skeletal muscle atrophy." (PMID 36497194, 2022).
muscular atrophy (1 paper, 2023). "Thus, further studies are warranted to explore and clarify the role of IL-18 and GSDMD in the progression of muscular atrophy and dysfunction in DMD." (PMID 37239853, 2023).
Myelopathy (1 paper, 2026). Myelopathy is an descriptive term, referring to pathology leading to a neurologic deficit related to the spinal cord. "We discuss current evidence of CAR-T-associated myelopathy, its proposed inflammatory and immune-trafficking mechanisms, and the potential contribution of interleukins and chemokines such as IL-1, IL-6, IL-18, CCL-2 and CXCL10 signaling to spinal cord injury." (PMID 41993175, 2026).
myocardial diseases (1 paper, 2016). "Microarray analysis revealed that interleukin-18 (IL-18), a pleiotropic cytokine involved in various myocardial diseases, was the most highly upregulated marker in FC-iPSC-CMs." (PMID 27888626, 2016).
Myocardial necrosis (1 paper, 2025). Irreversible damage to heart tissue (myocardium) due to lack of oxygen after a heart attack (myocardial infarction). "IL-8 and IL-6 were less strongly related to acute cardiac injury (not shown) and IL-18 levels were similar in those with versus those without myocardial necrosis." (PMID 39969260, 2025).
nosocomial infection (1 paper, 2022). An infection acquired in a hospital or other healthcare setting. "In the ROC analysis, the AUC for prediction of nosocomial infection using a combination of IL-6 and IL-18 at POD1 was 0.9616, while the AUCs for IL-6 alone and IL-12 alone were 0.8584 and 0.8256, respectively." (PMID 36299462, 2022). "The combined use of IL-6 and IL-18 levels at 0 hours postoperatively significantly improved the prediction of nosocomial infection." (PMID 36299462, 2022). "This indicated that the combination of early IL-6 and IL-18 levels was a good predictor of postoperative nosocomial infection in abdominal surgery recipients." (PMID 36299462, 2022). "The ROC curve further provided evidence that the combination of IL-6 and IL-18 could better predict the occurrence of postoperative nosocomial infection." (PMID 36299462, 2022). "Thus, these three inflammatory factors (IL-6, IL-12, and IL-18) are involved in the activation of the inflammatory response and are elevated in the early stages of nosocomial infection." (PMID 36299462, 2022). "According to the comparisons, we found significant differences in IL-6, IL-12, and IL-18 levels between the M-NI and M-NNI groups, which might be associated with the occurrence of postoperative nosocomial infections." (PMID 36299462, 2022).
obstructive jaundice (1 paper, 2015). A finding indicating increased bilirubin levels in the blood and urine, due to intrahepatic or extrahepatic obstruction of the biliary system. "IL-18, a member of the IL-1 cytokine family, was also reported to be obviously elevated in patients with obstructive jaundice, and returned to normal levels after the obstruction was relieved." (PMID 26292095, 2015).
ocular sarcoidosis (1 paper, 2023). A leading cause of inflammatory eye disease is sarcoidosis. "The following risk loci were observed for ocular sarcoidosis: rs2206593 near PTGS2 (p = 0.0096; OR = 2.20), and two variants near IL18, however with opposite directionality: rs1946518 (p = 0.006; OR = 1.61) and rs189667 (p = 0.004; OR = 0.59)." (PMID 37621457, 2023).
optic neuritis (1 paper, 2025). Optic neuritis is inflammation of the optic nerve, the nerve that carries the visual signal from the eye to the brain.The conditionmay cause sudden, reduced vision in the affected eye(s). "Patients with MOGAD showed higher IL6 (p = 0.036), IL8 (p = 0.012), and IL18 (p = 0.026) baseline levels compared with those with MS, in non–optic neuritis (ON) presentations." (PMID 39752619, 2025).
Oral ulcer (1 paper, 2025). Erosion of the mucous mebrane of the mouth with local excavation of the surface, resulting from the sloughing of inflammatory necrotic tissue. "The levels of inflammatory cytokines IL-6, TNF-α, IL-18, and IL-1β in the oral ulcer group were significantly higher than in the normal group." (PMID 40818135, 2025).
osteonecrosis (1 paper, 2025). A none disease characterized by death of bone tissue due to a lack of blood supply. "Plots from the leave-one-out analysis showed that there was no potentially significant SNP driving the causal relationship between osteonecrosis and IL-18, supporting our finding that the relationship was stable." (PMID 40760551, 2025). "Additionally, an increased risk of osteonecrosis may lead to decreased levels of IL-18." (PMID 40760551, 2025). "Only IL-18 may be a protective factor against osteonecrosis, according to reverse MR data (IVW OR = 0.97, 95% CI = 0.94–0.999, P = .042)." (PMID 40760551, 2025). "According to the IVW and MR-Egger analyses in the Cochran Q test, the results of the sensitivity analyses indicated that there was neither heterogeneity nor horizontal pleiotropy in the MR analysis of IL-18 on osteonecrosis (P > .05); this demonstrated the credibility of the causally robust results." (PMID 40760551, 2025).
otitis media with effusion (1 paper, 2021). Otitis media associated with accumulation of fluid in the middle ear. "Spearman correlation analysis between levels of caspase-1, IL-1β, and IL-18 in the middle ear effusion and the duration of otitis media with effusion." (PMID 34805037, 2021).
Pain (1 paper, 2015). An unpleasant sensory and emotional experience associated with actual or potential tissue damage, or described in terms of such damage. "Importantly, we have recently used these methods to suggest a role for the inflammasome (including elevated IL-18 and caspase-1) in a rat model of chronic neuropathic pain." (PMID 26635801, 2015).
papilloma (1 paper, 2011). A benign epithelial neoplasm that projects above the surrounding epithelial surface and consists of villous or arborescent outgrowths of fibrovascular stroma. "In contrast, mice with high levels of Il18 in their papillomas were most susceptible to tumor development." (PMID 21244661, 2011). "The IL1 family member IL18 (Il18) was expressed in skin and tumor samples, but only in carcinomas did Il18 have a strong cis-eQTL, with higher expression in papillomas from susceptible animals and when a SPRET/Ei allele was present (raw P = 2.6e-8, permutation P < 0.001, q = 0.001)." (PMID 21244661, 2011). "Unlike Il18, Gzme expression is not detectable in normal skin, and appears in papillomas and carcinomas concomitantly with the influx of innate immune cells." (PMID 21244661, 2011).
pemphigus (1 paper, 2025). Pemphigus is a group of rare autoimmune diseases that cause blistering of the skin and mucous membranes (mouth, nose, throat, eyes, and genitals).This conditioncan occur at any age, but often strikes people in middle or older age. "In the development and progression of pemphigus, NLRP inflammatory bodies, Caspase, IL-1 and IL-18, PRKN, and P2X are considered to be implicated." (PMID 40102153, 2025).
periapical tissue disease (1 paper, 2025). Any disease of the periapical tissue. "IL-6 positively correlated with decayed permanent teeth and pulp/periapical tissue diseases, whereas IL-18 correlated with white spot lesions and pulp infections." (PMID 40243946, 2025). "Additionally, a significant positive correlation was observed between salivary IL-18 concentration and the occurrence of white spot lesions (ICDAS-II codes 1–2) as well as pulp and periapical tissue diseases." (PMID 40243946, 2025).
peripheral artery disease (1 paper, 2018). "Recently, we showed that IL-18 expression was higher in patients with peripheral artery disease (PAD) than that in healthy controls; nonetheless, this finding did not achieve a statistically significant level." (PMID 29485097, 2018).
periventricular leukomalacia (1 paper, 2023). Periventricular leukomalacia (PVL) is a brain injury disorder characterized by the death of the white matter of the brain due to softening of the brain tissue. "In preterm infants with damaged periventricular white matter, known as periventricular leukomalacia (PVL), who later developed cerebral palsy, cord blood IL-18 was higher compared to healthy term infants." (PMID 36769133, 2023).
PFAPA syndrome (1 paper, 2022). An auto inflammatory syndrome characterized by recurrent febrile episodes associated with aphthous stomatitis, pharyngitis and cervical adenitis. "PFAPA syndrome is associated with elevated IL-1/IL-18, and IFN-γ gene signatures." (PMID 36203600, 2022).
pleural mesothelioma (1 paper, 2019). A neoplasm that arises from the mesothelial cells of the pleura. "Acting as a cluster, miR-411 and miR-379 inhibited the invasion of malignant pleural mesothelioma cells and appeared to decrease drug resistance (vorinostat (SAHA) and pemetrexed (PEM)) by directly targeting interleukin (IL)-18." (PMID 30390072, 2019).
polyarticular JIA (1 paper, 2023). "While the role of IL-18 pathway in systemic JIA is recognized, confirmation of IL-18 pathway involvement may suggest that some children with oligoarticular/polyarticular JIA are candidates for IL-1 targeted therapies." (PMID 36793127, 2023).
postmenopausal osteoporosis (1 paper, 2022). Metabolic disorder associated with fractures of the femoral neck, vertebrae, and distal forearm. "The immune system plays a critical role in bone homeostasis and, consequently, in the pathophysiology of postmenopausal osteoporosis (OP) since estrogen deficiency induces the inflammasome and increases production of pro-inflammatory cytokines, such as IL-1β and IL-18." (PMID 36553538, 2022).
primary effusion lymphoma (1 paper, 2024). A large B-cell lymphoma located in the body cavities, characterized by pleural, peritoneal, and pericardial fluid lymphomatous effusions and that is always associated with human herpes virus-8 (HHV-8). "Primary effusion lymphoma (PEL) cells show evidence of NRLP3 inflammasome activation, such as the presence of active caspase-1 and cleavage of pro-IL-1β and pro-IL-18." (PMID 38397043, 2024).
Psychotic episodes (1 paper, 2022). Periods of time during which an individual experiences significant disturbances in their thoughts, perceptions, emotions, and behavior, resulting in a loss of touch with reality. "Further support linking IL-18 signaling to SCZ was the finding that PC5course with positive loadings of IL-18R1, IL-18RAP and APRIL was negatively associated with severity of illness course as measured by rate of psychotic episodes, in these patients." (PMID 35856063, 2022).
renal adenocarcinoma (1 paper, 2021). "We demonstrated that sunitinib increased IL-1β, IL-6,IL-8 and IL-18 expression in cardiomyocytes and renal adenocarcinoma cells and that polydatin is able to significantly reduce their expression." (PMID 34178667, 2021).
renal infectious disease (1 paper, 2015). An infectious disease that involves the kidney. "Similarly, the likely roles of IL–18 polymorphism, another cytokine indicated in inflammasome-dependent innate immunity pathway in various kidney diseases, in pediatric renal infectious diseases would also require further investigations." (PMID 26444566, 2015).
renal tubular disease (1 paper, 2018). "In humans, IL-18 in the urine is one of the early markers of renal tubular disease." (PMID 29514661, 2018).
Respiratory tract infection (1 paper, 2025). An infection of the upper or lower respiratory tract. "We have demonstrated that recurrent respiratory tract infections were negatively correlated with IL-18 responses." (PMID 40661891, 2025). "Further research is required to determine the role of IL-18 in respiratory tract infections in children with SNI and whether it may prove useful as a therapeutic target." (PMID 40661891, 2025).
retinal degeneration (1 paper, 2019). Degeneration of the retina. "These hallmark pathogenic features are evident in both acquired and inherited forms of retinal degenerations, and are strongly correlated to the activation of the two most characterized IL-1 family members, IL-1β, and IL-18." (PMID 31379825, 2019). "However, in dry AMD, the literature points to a different contribution of IL-18 in retinal degenerations." (PMID 31379825, 2019). "Further investigations are required to elucidate the mechanisms by which IL-18 may have a role in regulating inflammation in retinal degenerations, including through the induction of interferon-gamma (IFN-γ), a cytokine thought to play a role in AMD." (PMID 31379825, 2019).
rickettsioses (1 paper, 2020). "The observed increase in cytokines, including monokine induced by IFN-γ (MIG), IP10 (IFN-γ-inducible 10-kDa protein), and IL-18 (also known as IFN-γ-inducing factor), indicate that an IFN-γ-related mechanism is contributing to the pathogenesis of severe rickettsioses." (PMID 31907196, 2020).
Right ventricular hypertrophy (1 paper, 2020). In this case the right ventricle is more muscular than normal, causing a characteristic boot-shaped (coeur-en-sabot) appearance as seen on anterior- posterior chest x-rays. "The overexpression of IL-18 in the lungs resulted in mild PAH and RV dilation, but the genetic ablation of IL-18 did not attenuate hypobaric hypoxia-induced PAH and right ventricular hypertrophy, suggesting that IL-18 may be a disease modifier, but it is not the causal factor for PAH development." (PMID 33105588, 2020).
scoliosis (1 paper, 2024). A congenital or acquired spinal deformity characterized by lateral curvature of the spine. "In addition, scoliosis was causally related to 4 common IFs, including T-cell surface glycoprotein CD6 isoform, hepatocyte growth factor, interleukin-18, and tumor necrosis factor ligand superfamily members." (PMID 38875409, 2024).
scrapie (1 paper, 2006). A fatal disease of the nervous system in sheep and goats, characterized by pruritus, debility, and locomotor incoordination. "In the present study, we evaluate if an exogenous treatment with Interleukin-12 (IL-12) and IL-18, able to activate microglia, is able to affect scrapie pathogenesis." (PMID 17192191, 2006). "we provided evidence that intracerebral administration of IL-12 and IL-18 stimulated microglia in central nervous system and that a single treatment contemporary to intracerebral scrapie injection is able to affect the course of scrapie infection." (PMID 17192191, 2006). "We can conclude that intracerebral administration of IL-12 and IL-18 can modulate scrapie pathogenesis possibly through a microglia-mediated pattern." (PMID 17192191, 2006). "Two groups of mice were injected intracerebrally with high dose of ME7 strain of scrapie containing IL-12 and IL-18 or sterile saline." (PMID 17192191, 2006). "It is our opinion, therefore, that these findings give credit to the hypothesis that IL-12 and IL-18-activated microglia are more efficient to uptake and to present scrapie agents to neurons." (PMID 17192191, 2006). "We further investigated the effect of combined IL-12 and IL-18 on scrapie pathogenesis." (PMID 17192191, 2006).
shigellosis (1 paper, 2012). Shigellosis is a bacterial infection leading to dysentery and is caused by Shigella, which are small, ubiquitous Gram-negative bacteria belonging to the enterobacteria family. "IL-18 mRNA down-regulation was also previously observed in an IL-8 supplemented mouse model of shigellosis, although rectal tissues from patients infected with S. dysenteriae show an influx (3 fold) of IL-18-expressing cells at the acute stage compared to healthy controls." (PMID 22675469, 2012).
sleep disorder (1 paper, 2025). A change from the patient's baseline sleeping pattern, in the hours slept and/or an alteration/dysfunction in the stages of sleep. "Sleep disorders are also associated with an increased systemic immune and inflammatory dysregulation, mainly due to hyperexpression of pro-inflammatory mediators and cytokines (e.g., IL-1β, IL-2, IL-6, TNF-α, IL-18, sTNF-R1, and sTNF-R2), and intermittent hypoxia-induced oxidative stress." (PMID 41156291, 2025).
spondylolisthesis (1 paper, 2026). A condition in which there is forward displacement of a vertebral bone over the on below it. "IP MR identified risk-increasing associations for LSS (4E-BP1 and interleukin-4), spondylolisthesis (CXCL1, CXCL5, FGF-5, IL-15RA, and IL-4) and IDD (IL-20RA and IL-6), while IL-18 showed a protective association with IDD that remained robust after multiple-testing correction." (PMID 42317351, 2026). "Mediation analyses identified 13 genetically supported putative GM-IPs-DLSD pathways, highlighting convergent mediators including PD-L1 for spondylolisthesis and IL-6 and IL-18 for IDD, with mediation proportions ranging from 7.55% to 13.22% across key pathways." (PMID 42317351, 2026).